AQP4 (aquaporin 4)
Diseases named in the same sentence as AQP4 in open-access papers (continued):
Sharing a sentence is not in itself a finding about the gene and the disease.
neuromyelitis optica spectrum disorder (continued). "Neuromyelitis optica spectrum disorder (NMOSD) is a rare but debilitating inflammatory and immune-mediated disease of the central nervous system (CNS) linked to the presence of disease-specific, pathogenic aquaporin 4-antibodies (AQP4-IgG) in the majority of patients (80%)." (PMID 39735550, 2024). "The discovery that AQP4-IgG can differentiate neuromyelitis optica (NMO) from multiple sclerosis (MS) has led to the concept of neuromyelitis optica spectrum disorder (NMOSD)." (PMID 37705973, 2023). "The characteristic demyelination pattern of neuromyelitis optica spectrum disorder (NMOSD) includes the II nerve, area postrema, spinal cord, and, rarely, brainstem and diencephalon, and is frequently associated with antibodies against aquaporin-4 (AQP4-NMOSD)." (PMID 37830631, 2023). "The International Panel for NMO Diagnosis achieved consensus that ON with aquaporin-4 antibody (AQP4-Ab) seropositivity can be diagnosed as neuromyelitis optica spectrum disorder related ON (NMOSD-ON) in 2015." (PMID 35945524, 2022). "Thus, GFAP levels in these body fluids may reflect the disease state of neuromyelitis optica spectrum disorder (NMOSD), which includes astrocytopathy, characterized by pathogenic antibodies against aquaporin 4 located on astrocytes." (PMID 35370870, 2022). "Indeed, experimental rodents lacking CD59 display enhanced demyelination in both experimental autoimmune encephalomyelitis and the Aquaporin 4-IgG injection model of neuromyelitis optica, in agreement with the view that CD59-expression protects against complement-mediated degeneration." (PMID 33898427, 2021). "AQP4 antibody and concomitant HSV-1 and HSV-1 infections have been associated with myeloradiculitis and encephalopathy; consequently AQP4 antibody test could be routinely used for HSV infection-mediated encephalopathy or neuromyelitis optica and autoimmune AQP4 channelopathy." (PMID 33796134, 2021). "Neuromyelitis optica spectrum disorder (NMOSD) is a rare inflammatory disease of the central nervous system (CNS) with a prevalence of 0.7-10/100,000 worldwide and is characterized by pathogenic complement-activating autoantibodies against aquaporin 4 (AQP4), the main water channel of the CNS." (PMID 33986750, 2021). "Likewise, inhibitory nanobodies could be targeted to aquaporin-4 to provide local complement inhibition and ameliorate the complement activating effect of autoantibodies in neuromyelitis optica." (PMID 33671302, 2021). "AQP4-IgG provides a means to distinguish NMO from MS and helps define neuromyelitis optica spectrum disorders (NMOSD)." (PMID 35082598, 2021). "Neuromyelitis optica (NMO) is a chronic, rare, inflammatory CNS disorder primarily manifesting as optic neuritis and longitudinally extensive transverse myelitis lesions and characterized by the presence of pathogenic autoantibodies (immunoglobulin G [IgG]) against aquaporin-4 (AQP4-IgG)." (PMID 34724990, 2021). "Although typical NMO is AQP4-IgG seropositive, some patients who present with the clinical characteristics of NMO are AQP4-IgG seronegative, therefore, use of the term of neuromyelitis optica spectrum disorder (NMOSD) is advocated." (PMID 34724990, 2021). "Neuromyelitis optica spectrum disorder (NMOSD) is an autoimmune-related neurological disorder that primarily causes astrocytic damage throughout the central nervous system and is characterized by the presence of serum anti-aquaporin-4 immunoglobulin G (AQP4-IgG)." (PMID 33013632, 2020). "Moreover, IL-6 may promote the survival of the plasma blasts that secrete immunoglobulin or pathological autoantibodies, e.g., anti-aquaporin 4 in patients with neuromyelitis optica (NMO)." (PMID 31523783, 2019). "Aquaporin-4-immunoglobulin G (AQP4-IgG) seropositive neuromyelitis optica spectrum disorder (herein called NMO) is an autoimmune demyelinating disease of the central nervous system." (PMID 30348195, 2018).
neuromyelitis optica spectrum disorder (continued). "The demyelination in neuromyelitis optica, a disorder related to multiple sclerosis, results from an autoimmune attack on aquaporin-4 in astrocytic foot processes; this may be relevant to other demyelinating conditions that could be triggered by mercury, since aquaporins are inhibited by mercury." (PMID 29959651, 2018). "Pathogenesis in aquaporin-4 immunoglobulin G (AQP4-IgG) seropositive neuromyelitis optica spectrum disorders (herein called NMO) involves complement-dependent cytotoxicity initiated by AQP4-IgG binding to astrocyte AQP4." (PMID 28750658, 2017). "73–90% of neuromyelitis optica spectrum disorder (NMOSD) patients diagnosed according to the 2015 International panel on NMO diagnosis have aquaporin-4 antibodies (AQP4-IgG)." (PMID 28840314, 2017). "The term “neuromyelitis optica spectrum disorders” (NMOsd) includes AQP4-IgG seropositive patients with NMO, but also other limited forms of the disease." (PMID 26950113, 2016). "However, with the discovery and validation of NMO-IgG in reductionist in vitro and in vivo models, it has become evident that astrocytic AQP4 may be the relevant target autoantigen in neuromyelitis optica instead of MOG which is expressed by oligodendrocytes." (PMID 21264240, 2011). "Another potential new role for AQP4 that is unrelated to its cell membrane water transport function was suggested by the discovery of circulating autoantibodies against AQP4 in most patients with the inflammatory demyelinating disease neuromyelitis optica (NMO)." (PMID 19660138, 2009). "Neuromyelitis optica spectrum disorders (NMOSD) refer to a severe autoimmune disease affecting the central nervous system, characterized by inflammatory demyelination, and the aquaporin-4 antibodies (AQP4-IgG) serve as a specific biomaker for NMOSD." (PMID 41586066, 2026). "In this study, we investigated a large cohort of patients with neuromyelitis optica spectrum disorders (NMOSD), pre‐classified based on serum IgG autoantibodies against AQP4 and MOG." (PMID 40103346, 2025). "Neuromyelitis optica spectrum disorder (NMOSD) is an inflammatory autoimmune disease that predominantly affects the optic nerves and spinal cord, with anti-aquaporin-4 antibody (AQP4-ab) recognized as its most prevalent biomarker." (PMID 41567208, 2025). "Neuromyelitis optica spectrum disorder (NMOSD) is an autoimmune disease of the central nervous system (CNS), in which the water channel protein Aquaporin-4 (AQP4) abundantly expressed on astrocytes is the target antigen." (PMID 39934927, 2025). "Epidemiology and pathophysiology: neuromyelitis optica spectrum disorder (NMOSD) is a rare autoimmune disease primarily affecting the optic nerves and spinal cord, characterized by the presence of anti-aquaporin-4 (AQP4) antibodies." (PMID 40687165, 2025). "Neuromyelitis optica spectrum disorder (NMOSD), an AQP4-IgG-mediated central nervous system demyelinating disease, is prone to recurrent disability." (PMID 41312352, 2025). "Neuromyelitis optica spectrum disorder (NMOSD) is a paradigmatic autoimmune disease of the central nervous system (CNS), in which the water channel protein Aquaporin-4 (AQP4) is targeted by a self-reactive immune response." (PMID 39934927, 2025). "Background and Clinical Significance: Neuromyelitis optica spectrum disorder (NMOSD) is a rare autoimmune demyelinating disorder of the central nervous system, characterized by the presence of aquaporin-4 (AQP4) antibodies and a high relapse rate." (PMID 40729219, 2025). "Background and Clinical Significance: Neuromyelitis optica (NMO) is a chronic demyelinating inflammatory disease of the central nervous system (CNS), mediated by autoantibodies against aquaporin-4 (AQ4) receptors." (PMID 40700243, 2025). "AQP4 and GFAP antibodies serve as key biomarkers for neuromyelitis optica spectrum disorders (NMOSD) and autoimmune GFAP astrocytopathy, respectively—two classical astrocytopathies." (PMID 40688088, 2025).
neuromyelitis optica spectrum disorder (continued). "Neuromyelitis optica spectrum disorder (NMOSD), driven by AQP4-IgG-producing B cells, is effectively managed with B cell depletion therapy (BCDT), such as rituximab (RTX)." (PMID 41246297, 2025). "Neuromyelitis Optica Spectrum Disorder (NMOSD) is a chronic autoimmune neuroinflammatory disease, typically characterized by antibodies against aquaporin 4 (AQP4-IgG) or myelin oligodendrocyte glycoprotein (MOG-IgG)." (PMID 41350239, 2025). "Neuromyelitis optica spectrum disorder (NMOSD) is an autoimmune demyelinating disease of the central nervous system, primarily affecting the optic nerves and spinal cord, mediated by aquaporin-4 (AQP4) immunoglobulin G (IgG) antibodies." (PMID 41312352, 2025). "Another study investigated the temporal adaptation of autoantigen-specific CD4+ T cells in neuromyelitis optica spectrum disorder (NMOSD), where the key autoantigen is aquaporin-4 (AQP4)." (PMID 40634636, 2025). "The discovery of aquaporin 4 immunoglobulin G (AQP4-IgG) autoantibody, present in ∼80% of patients with neuromyelitis optica spectrum disorder (NMOSD), dramatically improved its diagnosis, treatment, and prognosis." (PMID 40107294, 2025). "The discovery of antibodies AQP4 and myelin oligodendrocyte glycoprotein (MOG) has expanded our understanding of the pathogenesis of neuromyelitis optica." (PMID 39238786, 2024). "Based on the history, clinical findings, ophthalmologic examination, brain and neck imaging (MRI), and laboratory results (seropositive for anti-aquaporin 4 antibody), NMOSD with left retrobulbar neuritis (Devic's disease) was concluded as the final diagnosis." (PMID 39781148, 2024). "A 40-year-old woman with neuromyelitis optica spectrum disorder (NMOSD) and anti-aquaporin 4 antibodies suffered three NMOSD episodes between 35 and 37 years of age." (PMID 38550492, 2024). "Conventional rodent neuromyelitis optica spectrum disorder (NMOSD) models using patient-derived immunoglobulin G (IgG) are potentially affected by the differences between the human and rodent aquaporin-4 (AQP4) extracellular domains (ECDs)." (PMID 39125739, 2024). "Neuromyelitis Optica spectrum disorder (NMOSD) is an autoimmune relapsing disease of the brain and spinal cord where aquaporin-4 (AQP4) water channels are the main antigenic target." (PMID 38982999, 2023). "Neuromyelitis Optica Spectrum Disorder (NMOSD) is a demyelinating disease of the CNS, that targets aquaporin 4 (AQP4), an astrocyte water channel protein." (PMID 38002031, 2023). "Neuromyelitis optica spectrum disorders (NMOSD) are chronic inflammatory diseases of the central nervous system, characterized by autoantibodies against aquaporin-4." (PMID 37754247, 2023). "Neuromyelitis optica (NMOSD) is a rare relapsing autoimmune condition affecting central nervous system, pathogenically driven by anti-aquaporin 4 antibody activating terminal complement cascade with a resultant astrocyte damage and secondary demyelination." (PMID 37841263, 2023). "Neuromyelitis optica spectrum disorders (NMOSD) is an autoimmune disease of the central nervous system (CNS) mainly mediated by B cells and AQP4 antibody." (PMID 35851754, 2022). "Neuromyelitis optica spectrum disorder (NMOSD) is an autoimmune disease of the central nervous system (CNS) characterized by severe optic neuritis, myelitis, and the presence of anti-aquaporin 4 (AQP4) antibody (AQP4-Ab)." (PMID 34991631, 2022). "Neuromyelitis optica spectrum disorders (NMOSD), mainly mediated by B cells and AQP4 antibody, has a high rate of recurrence." (PMID 35851754, 2022). "Since the discovery of a specific autoantibody in patients with neuromyelitis optica spectrum disorder (NMOSD) in 2004, the water channel aquaporin-4 (AQP4) has attracted attention as a target of autoimmune diseases of the central nervous system." (PMID 35454180, 2022).
neuromyelitis optica spectrum disorder (continued). "Neuromyelitis optica spectrum disorder (NMOSD) is defined as a rare central nervous system, demyelinating, autoimmune disorder with autoantibodies against aquaporin-4." (PMID 35510001, 2022). "One such biomarker in the spinal fluid is myelin oligodendrocyte glycoprotein (MOG-IgG) and aquaporin-4 (AQP4), which are used to identify neuromyelitis optica spectrum disorders." (PMID 35187013, 2022). "Since the discovery of aquaporin-4 (AQP4) antibodies, neuromyelitis optica spectrum disorder (NMOSD) is defined as a neuro-inflammatory disease of the central nervous system (CNS), separate from multiple sclerosis." (PMID 35413922, 2022). "Neuromyelitis optica spectrum disorder (NMOSD) is an autoimmune inflammatory disorder of central nervous system (CNS) that attacks areas where water channel protein, aquaporin-4 (AQP4), is distributed." (PMID 35599732, 2022). "Detection of Aquaporin-4-antibodies (AQP4) in both serum and CSF led to diagnosis of AQP4-antibody positive neuromyelitis optica spectrum disorder (NMOSD)." (PMID 35585528, 2022). "Neuromyelitis optica spectrum disorder (NMOSD), a severe central nervous system (CNS) autoimmune disorder, is characterised by the presence of anti-aquaporin-4 (anti-AQP4) antibodies and chronic fatigue." (PMID 35091634, 2022). "One of the main differential diagnoses of MS is neuromyelitis optica (NMO), which is typically differentiated from MS by the presence of serum aquaporin 4 antibodies (AQP4-IgG)." (PMID 34327021, 2021). "Aquaporin 4 (AQP4)-specific antibodies (AQP4-abs) are found in the majority of patients with NMOSD and are termed neuromyelitis optica immunoglobulin G antibodies (NMO-IgG)." (PMID 34721390, 2021). "Here, we analyzed APRIL expression in a case of neuromyelitis optica (NMO), another autoimmune neurodegenerative disease, showing selective aquaporin-4 depletion in the spinal cord, complement deposition and infiltration of polymorphonuclear cells." (PMID 34421813, 2021). "Obwohl die Läsionen an eine Erkrankung wie die Neuromyelitis-optica-Spektrum-Erkrankung (NMOSD) denken lassen, waren nur vereinzelt Aquaporin-4- oder MOG(Myelinooligodendrozytenglykoprotein)-Antikörper nachweisbar." (PMID 33651117, 2021). "We report a case of a 47-year-old man who was initially diagnosed as neuromyelitis optica (NMO) on the basis of clinical findings, slightly high Aquaporin4 (AQP4) (1:10) and high signals of magnetic resonance imaging." (PMID 32161683, 2020). "Neuromyelitis optica spectrum disorder (NMOSD) patients, especially those with anti-aquaporin-4 antibody positivity, a water channel expressed on astrocytes, is often accompanied by autoimmune diseases (ADs) including Sjogren syndrome (SS)." (PMID 33157952, 2020). "Anti-AQP4 AAb is well known to be specific to neuromyelitis optica (NMO), also called Devic’s syndrome." (PMID 29632529, 2018). "Neuromyelitis optica spectrum disorders (NMOSD) are immune-mediated disorders in the central nervous system (CNS), and anti-aquporin-4 (AQP4) immunoglobulin G (IgG) is one of the major autoimmune antibodies that contributes the pathogenesis of NMOSD." (PMID 30131763, 2018). "Antibodies against AQP4 and AQP1 have been consistently observed in the sera from patients with neuromyelitis optica (NMO)." (PMID 30380700, 2018). "Neuromyelitis optica (NMO) and myasthenia gravis (MG) are autoimmune diseases mediated by autoantibodies against either aquaporin 4 (AQP4) or acetylcholine receptor (AChR), respectively." (PMID 29951558, 2018). "Reported prevalence rates of MOG-IgG seropositivity (based on cell-based assays) among patients with neuromyelitis optica spectrum disorder (NMOSD) and limited/related forms, according to phenotype and aquaporin-4 immunoglobulin G (AQP4-IgG) status." (PMID 29670575, 2018).
neuromyelitis optica spectrum disorder (continued). "For example: (i) in the presence of neuromyelitis optica immunoglobulin G, astrocyte‐destructive lesions can be initiated by CD4+ T cells when these cells recognize aquaporin 4 (AQP4), but also when they recognize other antigens of the central nervous system." (PMID 28344667, 2017). "Neuromyelitis optica (NMO) is a severe inflammatory demyelinating disease in CNS, and autoantibodies against aquaporin-4 (anti-AQP4), a water channel on astrocyte play a role in the pathology of NMO by triggering complement activation and ADCC." (PMID 28725222, 2017). "Neuromyelitis optica (NMO) is an inflammatory disease characterized by NMO immunoglobulin IgG (NMO-IgG), which is primarily considered to be an AQP4-specific antibody in NMO serum." (PMID 28174515, 2017). "In neuromyelitis optica spectrum disorder (NMOSD), a severe autoimmune central nervous system (CNS) inflammatory disease with autoantibodies reactive to aquaporin-4, there are few reports about fatigue and quality of life (QOL)." (PMID 28542592, 2017). "Studies of neuromyelitis optica (NMO), an autoimmune disease of the central nervous system (CNS), have demonstrated that autoantibodies against the water channel aquaporin-4 (AQP4) induce astrocyte damage through complement-dependent cytotoxicity (CDC)." (PMID 27905992, 2016). "Neuromyelitis optica (NMO) is an autoimmune disease consisting of recurrent optic neuritis and transverse myelitis, and serologic testing for the AQP4-immunoglobulin G (IgG) autoantibody is useful for a differential diagnosis from multiple sclerosis (MS)." (PMID 27517922, 2016). "Cell-based assays for neuromyelitis optica (NMO) diagnosis are the most sensitive and specific methods to detect anti-aquaporin 4 (AQP4) antibodies in serum, but some improvements in their quantitative and specificity capacities would be desirable." (PMID 24980919, 2014). "Hence, it was decided to pursue the testing of this antibody to find out the frequency of Anti-AQP4 Ig G amongst Malaysian patients presenting with a phenotype suggestive of NMO and other idiopathic inflammatory demyelinating diseases at high risk for neuromyelitis optica spectrum disorder (NMOSD)." (PMID 25548676, 2014). "Currently, autoantibodies to aquaporin-4 (AQP4), a water channel abundantly expressed in CNS astrocytes, are a widely accepted biomarker in patients suffering from neuromyelitis optica spectrum disorders (NMOsd)." (PMID 24086369, 2013). "An impressive example for the impact of the discovery of membrane-bound autoantigens was the very recent identification of Aquaporin-4 (AQP4), which is the principal cellular water channel of astrocytes, as autoantigen in neuromyelitis optica." (PMID 23236410, 2012). "Aquaporin 4 (AQP4)-specific autoantibodies in neuromyelitis optica (NMO) are immunoglobulin (Ig)G1, a T cell-dependent Ig subclass, indicating that AQP4-specific T cells participate in NMO pathogenesis." (PMID 22807325, 2012). "Patients with multiple sclerosis (MS), neuromyelitis optica spectrum disorders (NMOSD) with aquaporin-4 antibody-positive (AQP4-Abs-positive), and non-central nervous system (non-CNS) inflammatory diseases were chosen as controls." (PMID 41515652, 2026). "The concept of neuromyelitis optica spectrum disorder (NMOSD) is changing, with a disease spectrum emerging that includes aquaporin 4 (AQP4) IgG-seropositive NMOSD, myelin oligodendrocyte glycoprotein (MOG) antibody-associated disease (MOGAD), and double-seronegative NMOSD." (PMID 40951029, 2025). "Some patients with neuromyelitis optica spectrum disorder (NMOSD)-like symptoms test negative for anti-aquaporin-4 (anti-AQP4) antibodies." (PMID 39789036, 2025). "Autoantibodies against AQP4 and other ion channels, such as VGKC, have been found in autoimmune CNS diseases like neuromyelitis optica spectrum disorder and limbic encephalitis; accordingly, ion channels have also been investigated as potential antibody targets in multiple sclerosis." (PMID 41226806, 2025).